VCAM1 (vascular cell adhesion molecule 1)
Diseases named in the same sentence as VCAM1 in open-access papers (continued):
Sharing a sentence is not in itself a finding about the gene and the disease.
Hypertension (89 papers, 2005 to 2025). The presence of chronic increased pressure in the systemic arterial system. "Yin and colleagues demonstrated that inhibiting VCAM-1 with a monoclonal antibody reduces monocyte adhesion and infiltration into the endothelium, thereby protecting against arterial hypertension and dysfunction caused by Ang-2 in a mouse model." (PMID 40977717, 2025). "Multiple studies have demonstrated that elevated levels of IL-6, ICAM-1, and VCAM-1 are independently associated with incident hypertension, progression of atherosclerosis, and increased cardiovascular events." (PMID 40863231, 2025). "Endothelial expression of VCAM-1 is considered a link between common risk factors like aging, obesity, hypertension, and systemic inflammation and calcific aortic valve disease." (PMID 39765897, 2024). "VCAM-1 has previously been linked to LV wall thickness or LV mass indexes in patients with hypertension." (PMID 36001499, 2022). "Increased systemic (p<0.001) and intracranial (p=0.013) levels of VCAM1 were associated with the presence of hypertension." (PMID 33971895, 2021). "Furthermore, hypertension was associated with a significant increase of s-VCAM-1 in critical patients and with higher s-E-Selectin in VV-ECMO patients." (PMID 39862311, 2025). "In our study, the analysis of endothelial biomarkers in patients previously treated or untreated with RAAS blockers evidenced a similar impact to that of arterial hypertension, with endocan and VCAM-1 being significantly higher in treated patients." (PMID 39862311, 2025). "Significantly higher plasma levels of VCAM-1, as part of the hypertension pathophysiology, have been previously observed in many research studies, suggesting a close interconnection." (PMID 40977717, 2025). "Treatment with RAAS inhibitors prior to admission had a similar impact to that of hypertension on s-Endocan and s-VCAM-1." (PMID 39862311, 2025). "Taken together, these findings support a model in which Ang II–induced hypertension involves a VCAM1–chemokine axis–driven recruitment and activation of macrophages, rather than local macrophage expansion via CSF pathways." (PMID 41175639, 2025). "IL-1β (a pro-inflammatory cytokine), MCP-1 (a chemo-attractant cytokine), and VCAM-1 (an adhesion molecule) have been particularly highlighted in the context of endothelial cell dysfunction and hypertension." (PMID 40284196, 2025). "In the group of critical COVID-19 patients, the only marker affected by hypertension was s-VCAM-1, with significantly higher values being observed at admission and at days 3–4 (P = 0.010 and P = 0.045 vs. normotensive, respectively)." (PMID 39862311, 2025). "In contrast, age, hypertension, axial length, PED occurrence, GLD, and the expression levels of VEGF and VCAM-1 were negatively associated with the response to suboptimal ranibizumab treatment (P < 0.05)." (PMID 38260125, 2023). "Increasing evidence shows that VCAM-1 is closely related with the development of CVDs, such as ischemic cardiomyopathy, hypertension, coronary disease and atrial fibrillation." (PMID 36467095, 2022). "The current study reveals for the first time that VCAM-1 blockade ameliorates Ang II-induced hypertension and vascular dysfunction in mice." (PMID 35222039, 2022). "In conclusion, our data demonstrate for the first time that VCAM-1 activity is involved in Ang II-induced arterial hypertension and vascular dysfunction." (PMID 35222039, 2022). "For example, VCAM-1 level is augmented in arteries in Ang II-induced hypertension and sheep mitral valves after myocardial infarction." (PMID 36467095, 2022). "It has been reported that circulatory VCAM-1 levels are higher in older men with uncomplicated essential hypertension than in their normotensive peers and are positively correlated with SBP." (PMID 35222039, 2022).
Hypertension (continued). "The first goal was to assess how intracranial and systemic proteomic expression levels of VCAM1 differed according to comorbid conditions such as hypertension (HTN), smoking, and hyperlipidemia." (PMID 33971895, 2021). "In our cohort of ELVO ischemic stroke patients, proteomic expression of systemic and intracranial VCAM1 was studied relative to patient sex and comorbid conditions such as hypertension, dyslipidemia, and smoking status." (PMID 33971895, 2021). "VCAM-1 is considered as a biomarker and mediator in several cardiovascular disorders, including hypertension, stroke, and coronary heart disease, and is increased in ED." (PMID 34064366, 2021). "It is known that MR activation in endothelial cells contributes to cardiac inflammation and remodeling by promoting the expression of vascular cell adhesion molecule 1 (VCAM1), as shown in animal models of hypertension." (PMID 31507534, 2019). "Together with augmented expression of adhesion molecules such as P-selectin and VCAM-1, hypertension promotes an environment for enhanced peripheral immune cell entry to the brain." (PMID 30695999, 2019). "In contrast, soluble VCAM-1 (sVCAM-1) is elevated in older men with uncomplicated essential hypertension." (PMID 31223486, 2019). "IL-1β in essential hypertension enhances VCAM-1, ICAM-1, and E-selectin expression with atherosclerotic effects." (PMID 31186952, 2019). "Once activated by stimuli such as oxidized lipoproteins, hypertension, or hyperglycemia, vascular endothelial cells express VCAM-1, which enhances the recruitment and adhesion of monocytes to the endothelium." (PMID 26180602, 2015). "In experimental models of hypertension, the inhibition of NF-kB prevented ANGII-induced expression of IL-6, VCAM-1 and MCP-1, thus attenuating the inflammatory damage caused by ANGII." (PMID 20462420, 2010). "VCAM-1 is crucial for monocyte adhesion and migration to vascular endothelium, which, in chronic inflammation as seen in SAH patients, is linked to perpetuating hypertension." (PMID 40977717, 2025). "Besides, J. regia consumption improves endothelium‐dependent vasodilation, reduces VCAM‐1 levels, and decreases peripheral resistance, indicating its potential as a natural resource for functional foods or nutraceuticals targeting hypertension." (PMID 39803290, 2025). "We also showed that circulating PTX‐3 and VCAM‐1 concentrations were elevated with hypertension." (PMID 39414396, 2024). "Moreover, blocking of VCAM1 by a neutralizing antibody exhibits a protective effect against Ang II-induced arterial hypertension." (PMID 37168052, 2023). "So, the expression levels for AT1R and VCAM1 indicate the degree of hypertension." (PMID 37168052, 2023). "Other hypotheses suggest that activin A involvement in preeclampsia pathogenesis rely on endothelin-1, ICAM-1 and VCAM-1 overexpression, favouring hypertension and oedema." (PMID 37595293, 2023). "Our in vivo and in vitro results indicated that blocking VCAM-1 can effectively attenuate Ang II-induced hypertension and cardiac remodeling possibly by reducing VLA-4+ macrophage adhesion/migration and generation of IL-1β, IL6 and TNF-ɑ and ROS, as well as activation of multiple signaling pathway." (PMID 36467095, 2022). "To further explore the effect of VCAM-1 on hypertension and vascular remodeling, we administered a VCAM-1 neutralizing antibody (0.1 and 0.2 mg/mouse/day) or IgG control to WT mice for 1 day and then administered Ang II (490 ng kg−1 min−1) or saline via continuous infusion for up to 14 days." (PMID 35222039, 2022). "Furthermore, Ang II-caused hypertension, cardiac dysfunction, hypertrophy, fibrosis, infiltration of VLA-4+ BMMs and oxidative stress were dose-dependently attenuated in mice administered VCAM-1 neutralizing antibody." (PMID 36467095, 2022).
Hypertension (continued). "In our study, we found that Ang II infusion markedly upregulated VCAM-1 mRNA and protein expression in the mouse aorta and serum, indicating that an increase in VCAM-1 expression may be involved in the pathogenesis of hypertension and vascular dysfunction." (PMID 35222039, 2022). "Our data showed that the Ang II-induced increases in serum VCAM-1 levels and SBP were dose-dependently reduced in mice administered the VCAM-1 neutralizing antibody, indicating that the VCAM-1 neutralizing antibody effectively blocked VCAM-1 and inhibited hypertension in mice." (PMID 35222039, 2022). "For hypertension, we constructed a two-kidney and one-clip renovascular hypertensive (2K1C) mice model and found the expression of Smyd2 increased accompanied by upregulation of the senescence markers (p21, VCAM-1, and IL-6)." (PMID 36585926, 2022). "In conclusion, these results indicate that blockade of VCAM-1 exerts a protective effect against Ang II-induced arterial hypertension and dysfunction by regulating monocytes adhesion and infiltration into the endothelium and represents a novel therapeutic approach for hypertension." (PMID 35222039, 2022). "PC4d was also associated with pro-inflammatory markers such as hsCRP, IP-10, IL-6 and VCAM-1, and weakly with prednisolone treatment, but not with traditional cardiovascular disease risk factors, e.g. age, gender, current smoking and hypertension." (PMID 32259250, 2020). "Vascular cell adhesion molecule-1 (VCAM-1), intercellular adhesion molecule-1 (ICAM-1), and platelet endothelial cell adhesion molecule (PECAM) may be implicated in hypertension." (PMID 31223486, 2019). "In addition, VCAM-1 was reported to be a biochemical marker of left ventricular mass in patients with uncomplicated hypertension." (PMID 31223486, 2019). "Various stimulatory factors, including increased plasma lipid contents, hypertension, and pathogens, can lead to increased VCAM-1 expression in the endothelial cells,which attracts monocytes to adhere to the endothelium and further migrate to the vascular wall." (PMID 27386384, 2016). "L-NAME-treated mice exhibited hypertension, increased vascular cell adhesion molecule-1 and plasminogen activator inhibitor-1 mRNA levels in the aorta and impaired vasodilatation associated with decreased aortic eNOS expression, consistent with endothelial damage." (PMID 23525196, 2013). "The experimental model FFHR showed hypertension, dyslipidemia, insulin resistance, vascular and cardiac remodeling, inflammation demonstrated by increased hsCRP and vascular inflammation by increased the NF-κB expression, VCAM-1, and proatherogenic cytokines." (PMID 23365721, 2013). "Despite the absence of direct measurements of endothelial function, the greater circulating concentrations of VCAM‐1 in SHR as well as its association between VCAM‐1 concentrations and SBP in the present study support the role of endothelial activation in the development of hypertension." (PMID 39414396, 2024). "In our hypertension model induced by Ang II and in vitro study, we showed that the increase in the number of macrophages and the adhesion and migration of these cells to the endothelium are significantly inhibited by a VCAM-1 neutralizing antibody in a dose-dependent manner." (PMID 35222039, 2022). "Thus, an increase in VCAM-1 expression may play an important role in the development of Ang II-induced hypertension." (PMID 35222039, 2022). "Therefore, blockade of VCAM-1 represents a novel therapeutic option for hypertension." (PMID 35222039, 2022). "MetS symptoms, such as central obesity, dyslipidemia, insulin resistance (IR), and hypertension, are closely associated with vascular endothelial injury, increased intercellular cell adhesion molecule-1(ICAM-1), and vascular cell adhesion molecule-1 (VCAM-1); this promotes inflammation." (PMID 33628325, 2021).
Hypertension (continued). "Moreover, VCAM-1 but not ICAM-1 also associates with LVM in patients with uncomplicated essential hypertension, and in patients with hypertensive concentric LVH." (PMID 26398099, 2015). "The FFHR experimental model presents hypertension, dyslipidemia, insulin resistance, vascular and cardiac remodeling, inflammation demonstrated by increased hsCRP and vascular inflammation due to increased expression of NF-kB, VCAM-1 and pro-atherogenic cytokines." (PMID 25184237, 2014). "Moreover, age, CAD history, hypertension, low cholesterol (including total, LDL, and HDL cholesterol) levels, increased UACR, use of insulin therapy and antihypertensive drugs, and no use of statins or metformin were significantly associated with high serum VCAM-1 levels." (PMID 39355615, 2024). "However, the role of VCAM-1 in hypertension and vascular dysfunction remains largely unknown." (PMID 35222039, 2022). "Therefore, selective inhibition of VCAM-1 may be a promising therapeutic approach for hypertension." (PMID 35222039, 2022). "Monocyte recruitment is the key factor in the development of vascular inflammation, followed by adhesion molecules (VCAM-1 and ICAM-1), inflammatory factors (TNF-α and IL-6), and chemokines (CCL2, CXCL5, CXCL8, and CXCL10) released during hypertension." (PMID 34335249, 2021). "IL-1β stimulates the expression of vascular cell adhesion protein-1 (VCAM-1), intercellular adhesion molecule 1 (ICAM-1), and E-selectin in essential hypertension patients, which, in turn, results in unwanted atherosclerotic effects." (PMID 33494430, 2021). "Even after correction for clinically relevant cofounders (age, arterial hypertension, type 2 diabetes and LDL-cholesterol levels), VCAM-1 concentration [HF 1.001, 95% CI (1.0001–1.0018); p = 0.02] remained associated with the presence of PAD." (PMID 30535754, 2019). "Our current study shows that treatment with an HDAC8- 18 selective inhibitor suppresses the increased expression of VCAM-1 and ICAM-1 in Ang II- induced hypertension." (PMID 31223486, 2019). "Studies have shown that adhesion molecules ICAM-1, VCAM-1, immune cells, chemokine CCL2, and CXCR3 are key factors in human hypertension; these series of events results in the progression of hypertension." (PMID 29573749, 2018). "Mineralocorticoid receptor activation in ECs is known to contribute to the induction of cardiac inflammation and remodeling by promoting the expression of vascular cell adhesion molecule 1 (VCAM1), as shown in animal models of hypertension." (PMID 30231508, 2018). "In pre-/hypertension and in CAD, two studies only observed a reduction in VCAM-1 by regular cocoa consumption." (PMID 27240397, 2016). "We found an upregulation of VCAM-1 in brain endothelial cells of SHR, likely as consequence of an activated renin angiotensin system during arterial hypertension." (PMID 25519173, 2014). "Gene expression of ICAM-1, VCAM-1 and RANTES was unaltered whereas Osteopontin and MCP-1 were induced by hypertension." (PMID 15918915, 2005). "Arterial hypertension affected the values of s-Endocan, s-VCAM-1 and s-E-Selectin, but did not influence s-ICAM-1 concentration." (PMID 39862311, 2025). "The correlation among hypertension, AT1R, and VCAM1 has been reported as follows." (PMID 37168052, 2023). "In this sense, a longitudinal study on type 1 diabetes showed that higher levels of VCAM-1 (but not E-selectin or C-reactive protein) at baseline and through the 20-year follow-up period predicted the prevalence and incidence of hypertension." (PMID 37513556, 2023). "There was a significant difference of VCAM-1 levels on the boys with hypertension, lower on the hypertension boys compared to nonhypertension boys (9.01 ± 4.98 vs. 18.17 ± 21.78 pg/ml; p ≤ 0.001)." (PMID 37822716, 2023). "In the current study, we investigated whether blockade of VCAM-1 with a VCAM-1 neutralizing antibody prevents Ang II-induced adhesion and migration of macrophages and arterial hypertension." (PMID 35222039, 2022).
Hypertension (continued). "However, it was demonstrated that hypertension in patients with T2DM resulted in endothelial activation, reflected by increased levels of soluble adhesion molecules such as E-selectin and vascular cell adhesion molecule 1 (VCAM-1)." (PMID 30962800, 2019). "Through the induction of the coagulation cascade (PAI-1, TF, VCAM-1) and vasoregulatory activities (ACE, ET-1) PM2.5-AB transiently augments the hypertension and may contribute to the development and progression of atherosclerotic lesions." (PMID 20920269, 2010). "We found that blockade NLRP3 therapy markedly reversed hypertension, in consistent with the results reported by Krishnan, as well as significantly reduced NLRP3 pathway protein expression, decreased PICs, CCL2, CXCR3, and VCAM-1, adjusted TH, GAD67, and GABA in PVN and plasma NE." (PMID 29573749, 2018). "Participants with hypertensions had increased circulating myoglobin (p = 0.02) and LCN2/NGAL (p = 0.02), but no changes in VCAM-1 (p = 0.15) or platelets (p = 0.30)." (PMID 37598150, 2023). "Brain endothelial expression of intercellular adhesion molecule 1 (ICAM-1), vascular cell adhesion molecule 1 (VCAM-1), and P-selectin (CD62P) was neither increased by hypertension nor by stroke." (PMID 26640428, 2015). "Neither hypertension nor stroke had an impact on the endothelial expression of ICAM-1 and VCAM-1 at day 4 after PT." (PMID 26640428, 2015). "Leukocyte AM expression was not influenced by hypertension in naive rats, but by stroke: SHR exhibited a significantly increased MFI of ICAM-1 on myeloid leukocytes, whereas VCAM-1 and CD62P remained unchanged." (PMID 26640428, 2015). "Accordingly, it has previously been shown that levels of inflammatory regulators intracellular adhesion molecule (ICAM-1) and vascular cell adhesion molecule (VCAM-1) were upregulated immediately after the CPT in people with and without hypertension, compared to resting levels." (PMID 40597238, 2025).